TRAV9-1 (T cell receptor alpha variable 9-1)
Description:
V region of the variable domain of T cell receptor (TR) alpha chain that participates in the antigen recognition. Alpha-beta T cell receptors are antigen specific receptors which are essential to the immune response and are present on the cell surface of T lymphocytes. Recognize peptide-major histocompatibility (MH) (pMH) complexes that are displayed by antigen presenting cells (APC), a prerequisite for efficient T cell adaptive immunity against pathogens. Binding of alpha-beta TR to pMH complex initiates TR-CD3 clustering on the cell surface and intracellular activation of LCK that phosphorylates the ITAM motifs of CD3G, CD3D, CD3E and CD247 enabling the recruitment of ZAP70. In turn ZAP70 phosphorylates LAT, which recruits numerous signaling molecules to form the LAT signalosome. The LAT signalosome propagates signal branching to three major signaling pathways, the calcium, the mitogen-activated protein kinase (MAPK) kinase and the nuclear factor NF-kappa-B (NF-kB) pathways, leading to the mobilization of transcription factors that are critical for gene expression and essential for T cell growth and differentiation. The T cell repertoire is generated in the thymus, by V-(D)-J rearrangement. This repertoire is then shaped by intrathymic selection events to generate a peripheral T cell pool of self-MH restricted, non-autoaggressive T cells. Post-thymic interaction of alpha-beta TR with the pMH complexes shapes TR structural and functional avidity.
Synonyms: TCRAV9S1; TRAV91
Gene: T-cell receptor variable (V) gene on chromosome 14 (21,811,502 to 21,811,977, forward strand). Ensembl gene ENSG00000211783.
Subcellular location: Cell membrane
Gene Ontology:
Biological process: adaptive immune response
Cellular component: immunoglobulin complex; plasma membrane
Homologues: Orthologues: macaque TRAV9-1 (86% identical), mouse Trav6-5 (73% identical), mouse Trav6n-5 (71% identical), mouse Trav6d-5 (71% identical). Paralogues in human: TRAV9-2 (70% identical), TRAV18 (46% identical), TRAV40 (44% identical), TRAV19 (29% identical), IGKV1-12 (29% identical), IGKV1D-12 (29% identical), IGKV1OR2-108 (28% identical), TRDV1 (28% identical), IGKV1-17 (27% identical), IGKV1-39 (27% identical), IGKV1-5 (27% identical), IGKV1-9 (27% identical), and 81 more.